OVOL1 (ovo like transcriptional repressor 1)
Description:
Putative transcription factor. Involved in hair formation and spermatogenesis. May function in the differentiation and/or maintenance of the urogenital system (By similarity).
Synonyms: hOvo1
Tractability: No criterion of Open Targets' tractability assessment is met for any kind of drug.
Gene: Protein-coding gene on chromosome 11 (65,786,714 to 65,797,219, forward strand). Ensembl gene ENSG00000172818.
Subcellular location: Nucleus
Subcellular location (Human Protein Atlas): Nucleoplasm
Gene Ontology:
Molecular function: protein binding; sequence-specific double-stranded DNA binding; DNA-binding transcription factor activity, RNA polymerase II-specific; RNA polymerase II cis-regulatory region sequence-specific DNA binding; DNA-binding transcription repressor activity, RNA polymerase II-specific
Biological process: epidermal cell differentiation; regulation of transcription by RNA polymerase II; negative regulation of transcription by RNA polymerase II
Cellular component: nucleus
Genetic constraint (gnomAD): Loss-of-function variants: 13 observed, 23.72 expected, observed/expected ratio (o/e) 0.55, 90% interval 0.36 to 0.87. The upper end of that interval is the gene's LOEUF score, 0.87, which puts it in group 3 of 6, group 1 being the genes least tolerant of losing a copy. Missense variants: 277 observed, 361.77 expected, observed/expected ratio (o/e) 0.77, 90% interval 0.69 to 0.85. Synonymous variants: 129 observed, 150.91 expected, observed/expected ratio (o/e) 0.85, 90% interval 0.74 to 0.99.
Homologues: Orthologues: chimpanzee OVOL1 (99% identical), macaque OVOL1 (99% identical), mouse Ovol1 (96% identical), pig OVOL1 (96% identical), rat Ovol1 (94% identical), dog OVOL1 (93% identical), guinea pig OVOL1 (85% identical), rabbit OVOL1 (66% identical), Drosophila melanogaster ovo (51% identical). Paralogues in human: OVOL2 (52% identical), OVOL3 (35% identical), ZNF641 (24% identical), ZKSCAN2 (23% identical), ZNF18 (23% identical), PEG3 (22% identical), ZSCAN29 (22% identical), ZSCAN32 (22% identical), ZBTB35 (21% identical), ZNF202 (21% identical), ZNF518A (21% identical), ZSCAN5A (21% identical), and 17 more.
Diseases named in the same sentence as OVOL1 in open-access papers:
OVOL1 is named in the same sentence as 46 diseases in open-access papers, as found by Europe PMC text mining. Sharing a sentence is not in itself a finding about the gene and the disease. The quoted sentences say what the papers report.
breast carcinoma (9 papers, 2016 to 2025). "OVOL1 is highly expressed in ER + breast cancer, while RHOD has a causal role specifically in ER + breast cancer." (PMID 39720180, 2024). "This association is also supported by human eQTL studies in breast cancer, suggesting that rs3903072 may alter Ovol1 expression." (PMID 35087569, 2021). "As in breast carcinoma, higher OVOL1 expression has been correlated with prolonged relapse-free survival." (PMID 41230293, 2025). "Similar findings have been reported in oral SCC neoplasm as well as breast carcinoma, ovarian carcinoma, and renal cell carcinoma, where reduced OVOL1 expression correlates with more aggressive and invasive phenotypes." (PMID 41230293, 2025). "Furthermore, OVOL1 has demonstrated an inhibitory effect on breast cancer progression by enhancing the degradation of TGF‐β type I receptors." (PMID 40437660, 2025). "Moreover, OVOL1 agonists with higher specificity and in vivo safety can be explored to enable therapeutic gain for breast cancer patients." (PMID 35484112, 2022). "Moreover, 6-formylindolo(3,2-b)carbazole (FICZ) was identified as a compound to potently activate OVOL1 expression, which may offer therapeutic potential for breast cancer patients." (PMID 35484112, 2022). "We unraveled a novel mechanism by which OVOL1 attenuates TGF-β/SMAD signaling and maintains the epithelial identity of breast cancer cells." (PMID 35484112, 2022). "All these data suggest that restoration of OVOL1 expression by FICZ offers the prospect for therapeutic gain to mitigate overactive pro-oncogenic TGF-β signaling and breast cancer progression." (PMID 35484112, 2022). "Taken together, our data suggest that OVOL1 is a target gene of both BMP and TGF-β signaling in breast cancer cells." (PMID 35484112, 2022). "Here, we show that OVOL1 is inversely correlated with the epithelial–mesenchymal transition (EMT) signature, and is an indicator of a favorable prognosis for breast cancer patients." (PMID 35484112, 2022). "Our results uncover a novel mechanism by which OVOL1 attenuates TGF-β/SMAD signaling and maintains the epithelial identity of breast cancer cells." (PMID 35484112, 2022). "Since OVOL1 was identified as a suppressor of TGF-β/SMAD signaling and breast cancer progression, we focused on restoring OVOL1 expression by candidate small-molecule compounds." (PMID 35484112, 2022). "Taken together, our data suggest that OVOL1 expression is inversely correlated with EMT and is a potential indicator for a favorable prognosis in breast cancer patients." (PMID 35484112, 2022). "Given the inverse correlation between OVOL1 and EMP, we sought to examine the effect of OVOL1 depletion on EMT in breast cancer cells." (PMID 35484112, 2022). "In conclusion, our results implicate that OVOL1 mitigates the EMT, migration, extravasation, and early-phase metastatic events in breast cancer cells." (PMID 35484112, 2022). "We have identified FICZ as an activator to trigger OVOL1 expression and thereby suppressing TGF-β/SMAD signaling, EMT, migration and extravasation of breast cancer cells." (PMID 35484112, 2022). "Expression of the transcription factors OVOL1 and OVOL2 in mesenchymal prostate cancer and poorly differentiated breast cancer cells induces MET and so inhibits their metastatic potential." (PMID 27144453, 2016). "Interestingly, a significant inverse correlation between OVOL1 mRNA expression and the EMT signature was observed in four breast cancer patient cohorts." (PMID 35484112, 2022). "Moreover, a small-molecule compound 6-formylindolo(3,2-b)carbazole (FICZ) was identified to activate OVOL1 expression and thereby antagonizing (at least in part) TGF-β-mediated EMT and migration in breast cancer cells." (PMID 35484112, 2022). "Furthermore, we elucidate the mechanism by which OVOL1 attenuates TGF-β signaling and breast cancer metastasis." (PMID 35484112, 2022).
breast carcinoma (continued). "Although depletion of OVOL1 rescues, to some extent, the inhibitory effects of FICZ, other targets of FICZ may also contribute to its suppressive role in breast cancer progression." (PMID 35484112, 2022). "OVOL1 suppresses EMT, migration, extravasation, and early metastatic events of breast cancer cells." (PMID 35484112, 2022). "Considering the earlier finding that OVOL1 is expressed at very low to non-detectable levels in basal breast cancer cell lines, we speculated that the promoter of OVOL1 might be epigenetically silenced in these cells." (PMID 35484112, 2022).
atopic dermatitis (8 papers, 2018 to 2025). "OVOL1 has been previously associated with other complex traits, such as atopic dermatitis and metabolic conditions." (PMID 41075270, 2025). "Operating downstream of the Wnt/β‐catenin signalling cascade in both mice and Drosophila, OVOL1 has also been implicated in the suppression of atopic dermatitis through modulation of FLG expression in mouse keratinocytes." (PMID 40437660, 2025). "OVOL1 is also associated with atopic dermatitis, another type 2 inflammatory disease, and a recent meta-analysis study confirmed this susceptibility locus for eczema-associated asthma." (PMID 39197446, 2024). "In addition, previous study on atopic dermatitis demonstrated that OVOL1 regulates Filaggrin expression and Ovol1-deficient keratinocytes showed reduced expression of Filaggrin in the suprabasal compartment of epidermis." (PMID 38907248, 2024). "Notably, both FLG and OVOL1 were included among 31 genes identified as being significantly linked to susceptibility to atopic dermatitis by genome-wide association studies." (PMID 29866992, 2018). "The OVOL1-FLG axis contributes to the pathogenesis of atopic dermatitis, an allergic condition that is often comorbid with asthma and has shared genetics with asthma, likely mediated by disrupting barrier function." (PMID 40205616, 2025). "In addition, OVOL1 inhibition was involved in Filaggrin reduction, which might be involved in atopic dermatitis pathogenesis." (PMID 38907248, 2024). "In atopic dermatitis, it was found that AHR signaling increased the expression of OVOL1, which after its passage to the nucleus increased Filaggrin." (PMID 38907248, 2024).
asthma (6 papers, 2015 to 2025). "Although this is below our pre-defined posterior probability for colocalization (PP4) threshold of PP4 > 0.75, the finding is in line with previous results linking this locus with variation of specific digalactosylated structures (FA2FG2S1), expression of the OVOL1 gene and the risk of asthma." (PMID 38149987, 2023). "The four loci originally discovered through GWAS on eczema (FLG, IL4/KIF3A, OVOL1 and C11orf30/LRRC32) did not reveal an effect on asthma alone." (PMID 26542096, 2015).
eczema (5 papers, 2015 to 2025). "This study identified three new genes (OVOL1, ACTL9, KIF3A) that are associated with eczema." (PMID 30402607, 2017).
acne (4 papers, 2018 to 2026). An inflammatory process of the sebaceous glands which is characterized by comedones, nodules, papules and/or pustules on the skin. "OVOL1 was previously suggested as a potential candidate gene at the acne susceptibility locus at 11q13.1–13.2." (PMID 30542056, 2018). "A decrease in OVOL1 and TGFB2 expression in inflammatory acne papules compared to healthy skin of the same patients was also confirmed." (PMID 41351204, 2026). "In addition, the activity of the TGFβ signaling pathway is regulated by the transcription factor OVOL1 and the protein follistatin (encoded by FST), thus variations in these genes may influence sebocyte lipid synthesis and thus play a part in acne development and exacerbation." (PMID 33849530, 2021).
prostate carcinoma (4 papers, 2013 to 2022). A carcinoma that arises from epithelial cells of the prostate gland. "We demonstrated that in primary tumors of prostate cancer patients the expression of OVOL1 and OVOL2 highly correlate with E-cad expression, a critical marker of the differentiation state of these tumors." (PMID 24124593, 2013). "We recently demonstrated a novel function of the OVOL1 (ovo-like 1, Entrez GeneID 5017) and OVOL2 (ovo-like 2, GeneID 58495) TFs as critical inducers of MET in prostate cancer." (PMID 24612742, 2014). "In the prostate cancer model, we analyzed the following cell lines: PC3-EMT14-OVOL1 (OVOL1 overexpression), PC3-EMT14-OVOL2 (OVOL2 overexpression) and PC3-Epi (epithelial cells that express OVOL1 and OVOL2 and from which the mesenchymal PC3-EMT14 were initially obtained)." (PMID 24612742, 2014).
psoriasis (4 papers, 2022 to 2025). An autoimmune condition characterized by red, well-delineated plaques with silvery scales that are usually on the extensor surfaces and scalp. "OVOL1 loss leads to flaring of psoriasis-like inflammation and proliferation of epidermis in response to imiquimod (IMQ)." (PMID 38907248, 2024). "In conclusion, OVOL1 and filaggrin might be involved in psoriasis-associated inflammation and skin proliferation." (PMID 38907248, 2024). "OVOL1 and Filaggrin might be involved in psoriasis-associated inflammation and skin hyperproliferation." (PMID 38907248, 2024). "Thus, reduction of OVOL1 in psoriatic skin epidermis in this study might be the cause of epidermal hyperproliferation; which is the main feature of psoriasis." (PMID 38907248, 2024). "OVOL1 regulates epidermal barrier integrity and neutrophil accumulation in psoriasis-like inflammation." (PMID 41459538, 2025). "In the present work, we recorded a significant stepwise reduction in keratinocytes OVOL1 expression from controls to peri-lesional and psoriasis skin." (PMID 38907248, 2024). "In contrast, psoriasis dermis showed a significant overexpression of OVOL1 in inflammatory cells in relation to peri-lesional biopsies (P < 0.002)." (PMID 38907248, 2024). "They concluded that in mice, OVOL1 was altered by germline Ovol1 deletion and this inhibited the epidermal barrier, and potentiates psoriasis-like skin inflammation by promoting neutrophil attraction with formation of multiple abscesses." (PMID 38907248, 2024). "In contrast, there was a significant overexpression of OVOL1 in inflammatory cells in psoriasis dermis (169.61 ± 68.85) when compared to peri-lesional biopsies (112.14 ± 34.01) (P < 0.002)." (PMID 38907248, 2024). "OVOL1 and Filaggrin expression in epidermis showed a significant gradual reduction from normal skin to peri-lesional and psoriasis biopsies (P < 0.001)." (PMID 38907248, 2024). "OVOL1 demonstrated a significant direct correlation with Filaggrin expression in psoriasis (r = 0.568, P < 0.004)." (PMID 38907248, 2024). "Mouse Ovol1 promotes epidermal cell cycle arrest and suppresses psoriasis-like skin inflammation." (PMID 39939818, 2025). "In addition, PASI score categories mild (< 10), moderate and severe (> 20) cases showed a significant direct positive correlation with dermal H-score of OVOL1 in psoriasis skin (rs =0.494, p < 0.010)." (PMID 38907248, 2024). "Therefore, the expression and role of OVOL1 in psoriasis remained obscured and required further assessment." (PMID 38907248, 2024). "Taken together, it can be suggested that inhibition of OVOL1 could suppress Filaggrin function and discovering OVOL1 agonists may be beneficial in psoriasis treatment." (PMID 38907248, 2024). "The relation between Filaggrin and OVOL1 in psoriasis is still unclear." (PMID 38907248, 2024). "Therefore, OVOL1 agonist could play a role as a target therapy in psoriasis treatment." (PMID 38907248, 2024). "Indeed, OVOL1 controls the expression of FLG and a recent study revealed that lipid metabolism is the most altered metabolic pathway, with the notable up-regulation of PPARδ, in OVOL1 knock-out mice treated with imiquimod to induce psoriasis-like inflammation." (PMID 35216234, 2022).
Bowen disease (3 papers, 2020 to 2025). "They reported that OVOL1 expression was high in Bowen's disease but markedly reduced in squamous cell carcinoma (SCC)." (PMID 41230293, 2025). "OVOL1 and 2 protein levels are upregulated in benign precursor lesions of cSCC, such as AKs and Bowen’s disease (cSCC in situ) compared to cSCC." (PMID 35666359, 2022). "Moreover, we recently showed that human epidermis and hair follicles express OVOL1 and OVOL2, and that OVOL1/2 are overexpressed in Bowen disease and downregulated in cSCC." (PMID 32106476, 2020).
allergic disease (2 papers, 2020 to 2025). An immune response that occurs following re-exposure to an innocuous antigen, and that requires the presence of existing antibodies against that antigen. "Most pleiotropic associations were exhibited by rs479844 (AP5B1, OVOL1 genes), which was associated with dermatological and allergic diseases, and rs4072037 (MUC1 gene), which was associated with magnesium levels and gastroenterological cancer." (PMID 32637184, 2020).
gastric cancer (2 papers, 2023 to 2024). A primary or metastatic malignant neoplasm involving the stomach. "Elevated OVOL1 expression has been recognized in ovarian, breast, lung, and gastric cancers compared with their benign counterparts." (PMID 39509334, 2024). "The results showed that EMT‐promoting factors SNAI1 and SNAI2 were significantly downregulated, while EMT repressors GRHL2 and OVOL1 were significantly upregulated, suggesting that zyxin negatively regulates EMT in gastric cancer cells." (PMID 37667739, 2023).
lung carcinoma (2 papers, 2021 to 2025). "Proteomic analysis showed that the lung cancer process regulated by OVOL1 is strongly associated with cholesterol metabolism." (PMID 40437660, 2025). "Our study revealed a significant association between OVOL1 levels and lymph node metastasis and tumour stage in patients with non‐small cell lung cancer (NSCLC)." (PMID 40437660, 2025). "We next attempted to determine the potential mechanism by which OVOL1 regulates lung cancer proliferation and invasion." (PMID 40437660, 2025). "We constructed OVOL1 knockdown stable cell lines to further investigate its function in lung cancer cell lines." (PMID 40437660, 2025). "Our study demonstrated that knockdown of OVOL1 leads to impaired cholesterol metabolism in lung cancer cells." (PMID 40437660, 2025). "In conclusion, our investigation elucidates the pivotal role of OVOL1 in modulating the proliferation and metastasis of non‐small cell lung cancer (NSCLC) via its governance on APOE‐mediated cholesterol metabolic pathways." (PMID 40437660, 2025). "Despite these insights, the involvement of OVOL1 in lung cancer remains poorly understood." (PMID 40437660, 2025). "In agreement with the correlation analysis between β3 integrin and EMT markers, β3 integrin-overexpressing lung cancer cells showed increased mesenchymal markers, including N-cadherin, vimentin, and ZEB1; however, only small reductions were observed in E-cadherin, OVOL1, and ZO-1." (PMID 33883697, 2021).
lung squamous cell carcinoma (2 papers, 2020 to 2025). "OVOL1 expression was significantly higher in most malignant tumours, including lung adenocarcinoma (LUAD) and lung squamous cell carcinoma (LUSC)." (PMID 40437660, 2025).
skin cancer (2 papers, 2020). "Ovo-like transcriptional repressor 1 (OVOL1) and ovo-like zinc finger 2 (OVOL2) are important modulators of EMT in some tumors, but their roles in skin tumors remain elusive." (PMID 32106476, 2020). "However, the expression of OVOL1 and OVOL2 as well as their functions in skin neoplasms are poorly understood." (PMID 32106476, 2020).
bladder tumors (1 paper, 2024). "In the context of gemcitabine, the 5637GR bladder tumors had elevated expression of the OVOL1 target genes, including SOX2 and SOX9, in a OXCT1-dependent manner, resulting in greater mitotic index." (PMID 39509334, 2024).
cervical cancer (1 paper, 2017). A primary or metastatic malignant neoplasm involving the cervix. "We have also identified that the OVOL1 HPV master regulator positively correlates with mutation and neoantigen load in both data sets, pointing to a potential role in cervical cancer by controlling mesenchymal–epithelial transition." (PMID 28670312, 2017). "In addition, OVOL1 also represses c-Myc transcription, and as c-Myc level is a known poor prognostic factor in cervical cancer." (PMID 28670312, 2017). "Therefore, OVOL1 may play a complex role in regulating the growth and progression of cervical cancer." (PMID 28670312, 2017). "In the Human Protein Atlas, OVOL1 and PRDM1 showed low, ENO1 medium, while ZNF365 showed no protein expression in cervical cancer." (PMID 28670312, 2017).
glioblastoma (1 paper, 2022). The most malignant astrocytic tumor (WHO grade IV). "The TFs found in TR astrocyte, SIX3 has been discovered to suppresses glioblastoma cell growth and invasion via the WNT pathway whereas the TF OVOL1 has been found to participate in EMT in cancers such as breast and colon." (PMID 34976314, 2022).
hair loss (1 paper, 2025). "Therefore, OVOL1 and OVOL2 may represent potential therapeutic targets for the treatment of hair loss." (PMID 40671824, 2025).
male infertility (1 paper, 2019). The inability of the male to effect fertilization of an ovum after a specified period of unprotected intercourse. "Ablation of Ovol1 in mice led to abnormal male germ cell development and male infertility, and Ovol1 is essential for spermatogenesis." (PMID 31759386, 2019).
melanoma (1 paper, 2017). A malignant, usually aggressive tumor composed of atypical, neoplastic melanocytes. "Consistent with DNA methylation data, patients with high OVOL1 expression (H Score > median H Score) in the primary tumor had significantly better prognosis than those with low expression (H Score < median H Score), displaying both extended melanoma-specific and progression-free survival." (PMID 28578692, 2017).